CD24 (CD24 molecule)
Diseases named in the same sentence as CD24 in open-access papers (continued):
Sharing a sentence is not in itself a finding about the gene and the disease.
preeclampsia (3 papers, 2021 to 2023). Preeclampsia is a hypertensive disorder of pregnancy that is characterized by new-onset hypertension with proteinuria presenting after 20 weeks of gestation, and depending on mild or severe forms may initially present with severe headache, visual disturbances, and hyperreflexia. "Here, its reduced expression and protein levels were determined in the in vitro model of preeclampsia which is similar to the reduced CD24 found in early and preterm preeclampsia." (PMID 36555567, 2022). "In contrast, a higher expression of CD24 protein was found in term preeclampsia cases compared to term and preterm controls." (PMID 36555567, 2022). "Since, in the past, we showed that in preeclampsia cases there is a reduction in the expression of CD24, our results in this in-vitro model enable us to consider the reduced level of CD24 as an additional aspect of reduced immune tolerance in preeclampsia." (PMID 36555567, 2022). "When CD24 expression is limited such as in preeclampsia or BeWo trophoblasts transfected with STOX1A/B, the immunosuppression and immunotolerance fail to protect the pregnancy." (PMID 36555567, 2022). "The downregulation of CD24 was found in early and preterm preeclampsia; the higher impact of STOX1-B over STOX1-A may be related to their differential features as transcription factors in gene expression, as it was demonstrated earlier for other proteins." (PMID 36555567, 2022). "Moreover, in addition to mRNA reduction, it was found that in cases of early and preterm preeclampsia, immunohistochemistry labeling by CD24 was reduced in the syncytio-and-cytotrophoblasts, compared to preterm and term controls." (PMID 36555567, 2022). "CD24 is a mucin-like immunosuppressing glycoprotein whose levels increase during pregnancy and decrease in the syncytio- and cytotrophoblasts in early and preterm preeclampsia." (PMID 36555567, 2022). "In contrast to the normal course of pregnancy, in cases of early (before 34 weeks gestation), and preterm (before 37 weeks gestation) preeclampsia, the level of CD24 mRNA is reduced compared to cases of term delivery and preterm delivery (before 37 weeks gestation)." (PMID 36555567, 2022). "This direction may lead to exploring the supplement of CD24 as a therapeutic agent to fight preeclampsia." (PMID 36555567, 2022). "Therefore, a putative treatment with either CD24-Fc molecule or extracellular vesicles enriched with CD24 could serve as a potential therapy to cure preeclampsia." (PMID 36555567, 2022). "Since STOX1 suppresses CD24 which confers immune tolerance, this study indicates that there is an additional pathway for STOX1 involvement in the development of preeclampsia." (PMID 36555567, 2022).
skin carcinoma (3 papers, 2017 to 2025). "CD24 is expressed in skin tumors, with a strong indication of higher expression in tumor tissues as compared to their tissue of origin." (PMID 39136818, 2025).
thymoma (3 papers, 2021 to 2026). A neoplasm arising from the epithelial cells of the thymus. "Furthermore, we found that ST8SIA6 levels were positively correlated with CD24 levels in several cancers, including ACC, COAD, HNSC, rectal adenocarcinoma (READ), THCA, KIRP, thymoma (THYM), UCS, CESC, KIRC, and MESO." (PMID 39791710, 2024).
type 1 diabetes (3 papers, 2018 to 2024). "A similar phenomenon may explain why circulating switched memory B cells in individuals with type 1 diabetes also express lower levels of the adhesion molecule CD24." (PMID 29881878, 2018). "Healthy subjects had higher levels of galectin-10, CD24, CD197, CD196, CD25 and CD45RO and patients with type 1 diabetes had higher levels of CD16, CD45RA, CD274, HLA-DR, CD28, Interleukin (IL)-5R, and CD38." (PMID 37210405, 2023). "To evaluate the phenotypic characteristics of naive and memory B cells in individuals with type 1 diabetes, we developed a polychromatic flow cytometry panel incorporating a viability dye and monoclonal antibodies specific for CD3, CD19, CD21, CD24, CD27, CD38, CD45R/B220, CD95, CXCR3 and IgD." (PMID 29881878, 2018). "In contrast, no disease-specific alterations in the B cell compartment were detected in another study, designed to quantify the expression levels of CD19, CD24, CD27, CD38, IgD and IgM in individuals with type 1 diabetes and age- and sex-matched healthy donors." (PMID 29881878, 2018).
ZIKV infection (3 papers, 2018 to 2024). "As an alternative means of assessing the need for CD24 in Zika virus infection, both CD24 splice variants 1 and 7 were cloned from cDNA acquired from IMR-32 cells and sub-cloned into eukaryotic expression vectors (pcDNA6/CD24v1 and pcDNA5/CD24v7, respectively)." (PMID 30044847, 2018). "Most importantly, ectopic expression of CD24 in the ZIKV-restricted SK-N-AS cells converted them into a cell line that was now permissive to ZIKV infection." (PMID 36016357, 2022). "Basal and ZIKV infection-induced levels of IRF-1 were similarly fractionated in the case of CD24-low and -high cells, with the only apparent difference being the overall higher level of IRF-1 expression in CD24-low cells (compare lanes 2 and 6)." (PMID 36016357, 2022). "In both cell lines, IRF-1 was upregulated following ZIKV infection (lanes 2 and 4), to signals of 548,000 and 394,000 in CD24-low and –high cells, respectively." (PMID 36016357, 2022). "Therefore, they proposed that therapeutic ZIKV infection of individuals with CD24-positive tumors have a better prognosis, been a good prognostic marker in this treatment." (PMID 39347716, 2024). "We tested the hypothesis that the low-level permissivity of CD24-low cells to ZIKV infection could be overcome by increased MOI." (PMID 36016357, 2022). "We hypothesized that the low permissivity of CD24-low cells to ZIKV infection was due to a strong, basal antiviral response." (PMID 36016357, 2022). "Thus, ectopic CD24 expression alone was sufficient to increase the permissivity of an otherwise restricted ZIKV infection." (PMID 36016357, 2022). "Following ZIKV infection, CD24-low and -high cells showed no significant change in total STAT1 levels or STAT1 phosphorylation detected by Western blotting (comparing lanes 1 to 2 and lanes 3 to 4) or by immunofluorescence." (PMID 36016357, 2022).
anaemia (2 papers, 2023 to 2025). "It is worth noting that CD24 is not expressed in human erythrocytes, so targeted CD24 therapy does not result in anaemia as a side effect." (PMID 38137380, 2023).
Anxiety (2 papers, 2021 to 2023). Intense feelings of nervousness, tension, or panic often arise in response to interpersonal stresses. "Meanwhile, animal experiments showed that CD24 gene knockout improved anxiety-like behavior and cognitive performance in mice." (PMID 37547246, 2023). "Together with previous reports, these data emphasize the importance of CD24 to cognitive performance and anxiety and should be taken into consideration when using this model, which may lay the path for new therapies." (PMID 33562144, 2021). "Our results suggest that downregulation of CD24 may improve memory and anxiety-like behavior." (PMID 33562144, 2021). "Thus, in our CD24−/− mice, the lack of CD24 may have lowered the p38 MAPK pathway’s activation and reduced anxiety-like behavior." (PMID 33562144, 2021).
atherosclerosis (2 papers, 2016 to 2019). A disease characterized by the build-up of fatty material and calcium deposition in the arterial wall resulting in partial or complete occlusion of the arterial lumen. "GPI-anchored proteins, like CD24、CD87, can adjust the adhesion and migration of leukocytes, while the invasion and adhesion of leukocytes to endothelial cells is one of the key early events of atherosclerosis." (PMID 31077208, 2019).
auto-inflammatory syndromes (2 papers, 2021 to 2023). "A CD24-Fc fusion protein composed of the extracellular part of CD24 and the human IgG-Fc portion has shown encouraging results in clinical trials as a specific modulator of auto-inflammatory syndromes." (PMID 37346042, 2023). "More recently, the chimeric CD24-Fc protein has shown exciting results in clinical trials as a specific modulator of auto-inflammatory syndromes." (PMID 33915986, 2021).
benign prostate hyperplasias (2 papers, 2016 to 2024). "Therefore, the evaluation of CD24 expression can be included as one of the diagnosis options in cases of prostate enlargement." (PMID 39687458, 2024).
biliary tract cancer (2 papers, 2020 to 2024). "Conversely, the expression of CD24 on CD25+ CD24+ CD27+ B cells is positively correlated with biliary tract cancer, confirming CD24 as a risk factor and BAFF-R (B-cell activating factor receptor) as a protective factor.BAFF-R is a surface receptor found on B cells that specifically binds to BAFF." (PMID 39050844, 2024). "The results of the current study show that BAFF-R on IgD+ CD24-, BAFF-R on IgD- CD24-, and BAFF-R on naive-mature B cells are inversely associated with biliary tract cancer, contributing to the prognosis of patients with this condition." (PMID 39050844, 2024). "Similarly, the risk estimation for biliary tract cancer by CD25 on CD24+ CD27+ was 1.04, CD25 on CD24+ CD27+ showed a significant association with biliary tract cancer risk (OR=1.04, 95% CI=1.01–1.08, P=0.0074)." (PMID 39050844, 2024).
bladder urothelial carcinoma (2 papers, 2018 to 2024). "CD24 is a cornerstone of tumour progression in urothelial carcinoma of the bladder (UCB)." (PMID 30327565, 2018).
brain injury (2 papers, 2021 to 2025). Acute and chronic (see also brain INJURIES, CHRONIC) injuries to the brain, including the cerebral hemispheres, CEREBELLUM, and brain STEM. "However, our results contradict a recent report showing that the pharmacological blockade of CD24 worsened the cognitive impairment after traumatic brain injury." (PMID 33562144, 2021).
breast adenocarcinoma (2 papers, 2019 to 2024). "Our recent analyses have demonstrated positive downregulation of CD24 and EpCAM expression after oregano administration and decreased expression of CD24 and CD44 after treatment with clove buds in chemically-induced mammary adenocarcinomas in rats." (PMID 30970626, 2019).
breast ductal carcinomas (2 papers, 2011 to 2024). "Immunohistochemical analysis of CD44+CD24-/low expression and its relationship with hypoxia markers and clinical outcome were evaluated in 253 samples of breast ductal carcinomas." (PMID 21824412, 2011).
cancers of the larynx (2 papers, 2019). "CD24 expression was studied in 272 HNSCC cancers, including 85 cancers of the oral cavity, 82 cancers of the oropharynx, and 105 cancers of the larynx." (PMID 31661833, 2019).
chronic hepatitis B (2 papers, 2011 to 2023). "It was also reported that CD24 polymorphisms affect the progression of chronic hepatitis B infection." (PMID 37296834, 2023).
cognitive deficits (2 papers, 2021 to 2024). "A machine learning-based model, comprised of osteocalcin+, nephrin+, and CD24+ EVs predicted cognitive impairment in PWH on ART." (PMID 38725641, 2024). "For example, CD24 is extensively used to investigate cancer, and it has been shown that cancer patients often suffer from ‘cancer-related cognitive impairments (CRCI) in memory, attention and executive functions’." (PMID 33562144, 2021). "Even though CD24 knockout mice are used to investigate seemingly un-related models of cognitive deficits, these impairments should not be disregarded." (PMID 33562144, 2021).
colorectal adenoma (2 papers, 2015 to 2023). An adenoma that arises from the colon or rectum. "This study was aimed to evaluate the performance of the Micromedic CD24 assay in identifying colorectal adenoma using Western blot and ELISA assays." (PMID 37919766, 2023). "CD24 expression was detected in 90.7% of colorectal adenomas and 86.3% of CRCs compared to weak expression in only 16% of adjacent normal epithelium." (PMID 26078485, 2015). "A simple noninvasive blood test evaluating CD24 levels has high sensitivity and specificity for detecting colorectal adenomas and cancer in patients undergoing colonoscopy at an urban medical center." (PMID 26078485, 2015). "CD24 is expressed in 90% of colorectal adenomas and adenocarcinomas." (PMID 26078485, 2015). "Elevated levels of CD24 may be indicative of colorectal adenoma." (PMID 37919766, 2023).
colorectal polyps (2 papers, 2022 to 2023). "A series of studies have indicated that CD24 increased with age, the diameter of colorectal polyps, the type of dysplasia of colorectal polyps, the metastasis of CRC, and the degree of differentiation of CRC, which showed a significant positive correlation." (PMID 37919766, 2023). "The increase in the expression rate of CD24 can be used as the basis for the malignant transformation of colorectal polyps." (PMID 35938128, 2022). "Studies have shown that the positive rate of CD24 is as high as 60% when the diameter of colorectal polyp is less than 2.0 cm." (PMID 35938128, 2022). "Moreover, CD24 increased with age, the diameter of colorectal polyps, the type of dysplasia of colorectal polyps, the metastasis of CRC, and the degree of differentiation of CRC, which showed a significant positive correlation." (PMID 35938128, 2022). "Therefore, early analysis of CD24 expression can reduce the probability of colorectal polyps deteriorating into CRC and promote the prognosis of CRC." (PMID 35938128, 2022). "With the increase in the diameter of colorectal polyps, the degree of polyp dysplasia, and the degree of differentiation of CRC, the expression rate of CD24 increases." (PMID 35938128, 2022).
Crohn disease (2 papers, 2017). A gastrointestinal disorder characterized by chronic inflammation involving all layers of the intestinal wall, noncaseating granulomas affecting the intestinal wall and regional lymph nodes, and transmural fibrosis. "In the Israeli population, individuals with CD24 rs8734 polymorphisms had an increased risk of IBD, ulcerative colitis, and Crohn’s disease." (PMID 28702029, 2017).
fatty liver (2 papers, 2018 to 2023). "The goal of this study was to evaluate the diagnostic accuracy of CD24 gene expression as a non-invasive tool to detect hepatic steatosis for diagnosis of NAFLD at early stage." (PMID 36900128, 2023). "This could indicate that CD24 may contribute to hepatic steatosis, but a current study showed that it cannot be used as an independent predictor of NAFLD." (PMID 36900128, 2023). "To further determine which genes might play a significant role in the progression of fatty liver, we used real-time qPCR to detect the expression of 8 DEGs using clinical samples, including CD24, PZP, COL1A1, COL1A2, LUM, VCAN, THBS2 and EPHA3." (PMID 29769552, 2018).
gallbladder carcinoma (2 papers, 2016 to 2024). "Furthermore, CD24 overexpression in primary gallbladder carcinoma (GBC) correlates with Lymph node spread and invasion into lymphatic and vascular channels, and the worst prognosis was observed in patients with primary gallbladder carcinoma who were in the CD24+ subgroup." (PMID 39050844, 2024).
gastric tumor (2 papers, 2016 to 2025). "CD24 and EGFR expression patterns in human gastric tumor samples were also investigated by immunohistochemistry staining." (PMID 26830684, 2016).
germ cell tumor (2 papers, 2022 to 2024). A benign or malignant, gonadal or extragonadal neoplasm that originates from germ cells. "The expression level of CD24 was negatively correlated with the activation of CD4+ and CD8+ T cells in testicular germ cell tumors (TGCT), THCA, CESC, and KIRP." (PMID 39791710, 2024).
heart failure (2 papers, 2011 to 2021). Inability of the heart to pump blood at an adequate rate to meet tissue metabolic requirements. "As we learn that myocardial ischemia and heart failure are propagated by aberrant local immune response, the role of CD24 in the development of immune tolerance, perhaps through augmentation of regulatory B-cells sub- populations, makes it an interesting new focus to study." (PMID 33915986, 2021).
Hepatitis (2 papers, 2021 to 2024). Inflammation of the liver. "Of note, also the HBvac NR who was the only individual without protective anti-HBs titer even after booster with third-generation hepatitis B vaccine had very low frequencies of IL-10 expressing CD24+CD27+ and CD24highCD38high Breg and B10+ cells." (PMID 34566969, 2021). "We performed comparative phenotypic and frequency analysis of Breg subsets (CD24+CD27+ and CD24highCD38high Breg) in second-generation hepatitis B vaccine non-responders (2nd HBvac NR, n = 11) and responders (2nd HBvac R, n = 8) before (d0), on day 7 (d7), and 28 (d28) after booster vaccination." (PMID 34566969, 2021). "Interestingly we did not observe decreased numbers of CD24+CD27+ and CD24highCD38high Breg post-boost with the second-generation hepatitis B vaccine." (PMID 34566969, 2021).
liver cirrhosis (2 papers, 2018 to 2021). "Among them, CCL5, CXCL9, CXCL12, LCK and CD24, which are thought to participate in the immune response, were identified as the most affected genes, suggesting a disruption of the immune response in liver cirrhosis." (PMID 34434654, 2021).
lymphopenia (2 papers, 2014 to 2025). Reduction in the number of lymphocytes. "Lymphoid cell distribution revealed a CD19+ B cell lymphopenia (5%) with a reduction in CD24++CD38++ transitional B cell percentage (0.7%)." (PMID 39860371, 2025). "The absolute numbers of CD19+CD5+CD1dhigh cells, CD19+CD24+CD38+ cells, and CD19+IL-10+ cells increased but not significantly in SLE patients when compared with healthy controls, which might be attributed to peripheral lymphopenia in SLE patients during flares." (PMID 24551101, 2014).
malignant mesothelioma (2 papers, 2014 to 2025). A malignant neoplasm of the pleura or peritoneum, arising from mesothelial cells. "In a study of malignant mesothelioma, CD26/CD24-deficient cell lines grew slower, were less invasive but more sensitive to drug therapy." (PMID 40486886, 2025). "CD24 has also been identified as one of the cancer stem cell markers in human malignant mesothelioma cells." (PMID 24612587, 2014). "CD24 induces high expression of pluripotent stem cells in malignant mesothelioma." (PMID 40486886, 2025). "It suggested that molecular radiotherapy targeting CD26 and CD24 may be a promising approach to targeted therapy against malignant mesothelioma CSCs." (PMID 40486886, 2025).
malignant neoplasms of the salivary glands (2 papers, 2014 to 2016). "It is also reported that CD24 expression positively associated with salivary gland cancer stage III/IV." (PMID 24612587, 2014). "CD24+/CD44+ subpopulation identified in our study may represent a new subtype of the cancer stem cells in HNSCC, specifically in salivary gland malignant neoplasms." (PMID 24612587, 2014).
metastatic colorectal cancer (2 papers, 2019 to 2020). "CD24 genetic variants may help select patients with metastatic colorectal cancer most likely to benefit from cetuximab-based therapy." (PMID 33065994, 2020). "Recently, it was shown that in CTC of NSCLC patients the CD44(+)/CD24(−) population possess epithelial–mesenchymal transition characteristics, while another study in metastatic colorectal cancer has shown the prognostic significance of CTC that express both EMT and stem-like genes." (PMID 31261917, 2019).
mucoepidermoid carcinoma (2 papers, 2013 to 2015). A carcinoma morphologically characterized the presence of cuboidal mucous cells, goblet-like mucous cells, squamoid cells, cystic changes, and a fibrotic stromal formation. "However, the CD24 displayed focal weak to moderate membranous/citoplasmatic staining in SGMN (mucoepidermoid carcinoma 3 cases), adenoid cystic carcinoma (12 cases), carcinoma ex-pleomorphic adenoma (1 case), and salivary duct carcinoma (2 cases)." (PMID 23419168, 2013). "Here, we investigated the expression of putative cancer stem cell markers (ALDH, CD10, CD24, CD44) in primary human mucoepidermoid carcinomas by immunofluorescence, in vitro salisphere assays, and in vivo tumorigenicity assays in immunodeficient mice." (PMID 26449187, 2015).